KIF5B (kinesin family member 5B)
Diseases named in the same sentence as KIF5B in open-access papers (continued):
Sharing a sentence is not in itself a finding about the gene and the disease.
lung adenocarcinoma (continued). "In at least two out of these four cases (KIF5B–MET in lung adenocarcinoma and TFG–MET in thyroid papillary carcinoma), the predicted chimeric protein follows the classic activation paradigm, fusing dimerization motifs to an intact kinase domain." (PMID 25204415, 2014). "Recently, RET gene rearrangements with N-terminal of KIF5B gene were identified in lung adenocarcinomas from large-scale sequencing." (PMID 23342255, 2012). "The recent study has been reporting the novel KIF5B/RET gene rearrangement found to occur in 2% (9/405) of Asian lung adenocarcinoma patients screened." (PMID 23342255, 2012). "Further screening of 561 lung adenocarcinomas identified 11 additional tumors with KIF5B-RET gene fusions." (PMID 22928112, 2012). "In a similar study, using a next-generation sequencing assay targeting 145 cancer-relevant genes in 24 non-small-cell lung cancer formalin-fixed paraffin-embedded tissue specimens identified KIF5B-RET fusion in lung adenocarcinoma." (PMID 22928112, 2012). "The research of lenvatinib on KIF5B RET positive adenocarcinoma of the lung has entered phase II (nct01877083), and its clinical experiments combined with pembrolizumab on non-small cell lung cancer has entered phase III (nct03829332, nct04676412, nct03976375)." (PMID 38164168, 2024). "Case 2 was a 74-year-old male with KIF5B-RET-rearranged stage IVA (cT1bN3M1b) lung adenocarcinoma." (PMID 32295619, 2020). "This collection included the previously reported LC-2/ad cell line that harbors a CCDC6-RET fusion (xxxxx) as well as two novel patient-derived cell lines generated by us, i.e. ECLC5B harboring TRIM33-RET and PDX-derived lung adenocarcinoma cells harboring KIF5B-RET (LUAD-0002AS1)." (PMID 33318047, 2020). "Taken together, our data suggest one-step screening platform for KIF5B-RET as well as EGFR, K-RAS, ALK oncogenic mutations be necessary for lung adenocarcinoma patients because EGFR or KRAS mutation are not infrequently found in KIF5B-RET-positive patients." (PMID 26268359, 2015). "In contrast to previous reports, our results indicate that the KIF5B-RET fusion gene may coincide with EGFR or KRAS mutations, albeit at a lower frequency, in lung adenocarcinomas." (PMID 26268359, 2015). ", we could only confirm the existence of 3/270 (1.1%) the KIF5B/RET rearrangements in lung adenocarcinomas." (PMID 23342255, 2012). "Thus, we have successfully introduced FISH for diagnosing KIF5B/RET positive lung adenocarcinoma." (PMID 23342255, 2012). "RET is a fusion gene involving kinesin family member 5B (KIF5B) as a fusion partner, present in up to 1.7% of patients with lung adenocarcinomas." (PMID 26371045, 2015). "Case 1 was a 55-year-old female never smoker, with KIF5B-RET-rearranged lung adenocarcinoma and brain metastasis, was treated with second-line cabozantinib." (PMID 32295619, 2020). "The KIF5B-RET rearrangement is detected with the frequency of 1 ~ 2 % in ‘triple marker’-negative lung adenocarcinomas, i.e., EGFR, KRAS and EML4-ALK wild type." (PMID 26268359, 2015). "The KIF5B-RET fusion gene is capable of inducing the abnormal proliferation and differentiation of tumor cells through the constitutional overexpression and activation of the RET proto-oncogene, ultimately leading to lung adenocarcinomas." (PMID 26268359, 2015).
non-small cell lung carcinoma (17 papers, 2012 to 2025). A group of at least three distinct histological types of lung cancer, including non-small cell squamous cell carcinoma, adenocarcinoma, and large cell carcinoma. "In general, KIF5B-RET fusions are most commonly oncogenic drivers of non-small-cell lung cancers (approx. 1–2% of all cases) and can be treated successfully with selpercatinib." (PMID 38672643, 2024). "Here, we present a case of a 56-year-old woman diagnosed with KIF5B-MET fusion-positive non-small cell lung cancer who had a durable response to capmatinib after acquired resistance to telisotuzumab vedotin." (PMID 36033470, 2022). "In roughly 1% of non small cell lung cancers (NSCLC), particularly in adenocarcinoma, chromosomal inversions cause the fusion of the RET-encoded TK domain to different exons of KIF5B (kinesin family member 5B) gene or, less commonly, to CCDC6, NCOA4 or TRIMM33." (PMID 26046350, 2015). "KIF5B-RET fusion is an oncogene identified in non-small cell lung cancers." (PMID 25047660, 2014). "Specifically, the product of KIF5B-RET activated multiple RTKs, including EGFR, providing vulnerabilities that could be targeted using combinations such as sorafenib with erlotinib or paclitaxel as potential treatment options for KIF5B-RET-positive non-small cell lung cancer (NSCLC)." (PMID 39722550, 2025). "RET kinase domain fusion with kinesin family member 5B was identified in about 1–2% of patients with non-small-cell lung cancer (NSCLC), who were negative for mutations or rearrangements in other common oncogenic drivers such as EGFR, HER, ERBB2, BRAF, KRAS, ALK, etc.." (PMID 32993133, 2020). "Using a genomics guided outlier approach, we identified 4 RET fusion PDX models with 3 different fusion partners (KIF5B, CCDC6, and NCOA4) in both non-small cell lung cancer and colorectal cancer." (PMID 30038711, 2018). "Somatic RET rearrangements (as fusion genes with CCDC6, NCOA4, KIF5B, PRKAR1A, TRIM33 and other rarer partners) have now been found in 1–2% of non-small-cell lung cancers (NSCLC) and at lower prevalence in many other cancers including pancreatic, colon, breast and salivary gland." (PMID 39655713, 2025).
breast carcinoma (12 papers, 2018 to 2024). "KLC1 has also been found to interact with KIF5B, regulating cell-cell adhesion, and epithelial-mesenchymal plasticity in breast cancer." (PMID 38923999, 2024). "Similarly, the kinesine-1 subunits kinesin family member 5B (KIF5B)/kinesin light chain 1 (KLC1) modulate the EMP process differently in breast cancer, with KIF5B being an inducer of EMT and KLC1 being its suppressor." (PMID 36890838, 2023). "The very rare KIF5B-RET gene fusion, previously found only in a few breast cancer patients, can be treated with the FDA-approved targeted RET inhibitor selpercatinib." (PMID 38672643, 2024). "Our study confirms at several levels that SHTN1 and KIF5B interact with both PRMT5 and RELA in luminal A breast cancer cells." (PMID 38417630, 2024). "Since it has been reported that KIF5B mediates MT1-MMP intracellular trafficking in primary macrophages and breast cancer cell line, MDA-MB231, we also re-examined KIF5B knockdown in HT-1080 cells." (PMID 35122963, 2022). "The molecules involved in MT1-MMP trafficking and the contribution to breast cancer invasion is possibly due to the ARF6 and kinesin-1/KIF5B." (PMID 29642589, 2018).
diabetes (5 papers, 2013 to 2024). "In this regard, GAP-43 and KIF5B protein levels in the DC group were significantly lower than those in the C group, indicating that diabetes caused a decreased expression of these proteins in the gastrocnemius skeletal muscle fibers (p ≤ 0.001 and p ≤ 0.001, respectively)." (PMID 33953268, 2021). "Growing evidence indicates that KIF5B-driven axonal transport is impaired in diabetes mellitus, probably contributing to the development of subsequently diabetic neurological complications." (PMID 33953268, 2021). "Our other finding was that diabetes significantly decreased the KIF5B protein levels in gastrocnemius muscles." (PMID 33953268, 2021). "Determining the relationship between KIF5B, mitochondrial dysfunction and aggregation filaments in diabetes is unclear, and it is an interesting topic for future studies." (PMID 33953268, 2021). "In agreement with previous observations obtained in male hippocampus, diabetes induced a significant increase of KIF5B mRNA expression in male DRG (Bonferroni post hoc analysis, p < 0.01)." (PMID 29351809, 2018). "Increased mRNA expression of KIF1A (increase to 1.92±0.6 of the control) and KIF5B (increase to 1.39±0.2 of the control) were detected after 2 weeks of diabetes." (PMID 23776493, 2013). "At 2 weeks of diabetes, KIF5B mRNA levels were also increased (increase to 1.39±0.3), but no significant changes were observed in KIF5B immunoreactivity in the hippocampus by Western blotting." (PMID 23776493, 2013). "KIF5B-deficient beta cells will thus serve as an ideal system for studying a Ca2+- or SFK-independent component of first-phase GSIS, which will contribute to next-generation diabetes therapeutics." (PMID 39322740, 2024). "Finaly, the results of double-immunostained labeling of KIF5B and GAP-43 protein expression in the rat gastrocnemius muscle showed that compared with the C group, diabetes caused a decreased of KIF5B+ Cells (% GAP-43+) in the gastrocnemius skeletal muscle fibers (p ≤ 0.001)." (PMID 33953268, 2021). "An overexpression of KIF5B was also found in the hippocampal at 2 weeks of diabetes." (PMID 29351809, 2018). "However, at 8 weeks of diabetes, the mRNA expression significantly increased to 1.56±0.3, and KIF5B protein levels increased to 127.7±9.3% of the control." (PMID 23776493, 2013). "One study has reported that the KIF5B gene mediates plasma membrane translocation of the glucose transporter type 4, ablation of which may lead to glucose intolerance, insulin resistance, and diabetes." (PMID 33200553, 2020). "In conclusion, the present study shows that diabetes decreases GAP-43 and KIF5B protein levels in gastrocnemius muscle of STZ-induced diabetic rats and as a non-pharmacologic therapeutic intervention, ET can modify it." (PMID 33953268, 2021). "Specifically, we showed that short-term diabetes alters both the mRNA levels and axoplasm content of KIF1A and KIF5B and axoplasm content of KIF5A and Myosin Va, but only in male animals." (PMID 29351809, 2018). "Specifically, we showed that diabetes alters the mRNA levels, and immunoreactivity of KIF1A and KIF5B motor proteins in the hippocampus of diabetic rats." (PMID 23776493, 2013). "We investigated the effect of diabetes (2 and 8 weeks duration) on KIF1A, KIF5B and dynein motor proteins, which are important for axonal transport, in the hippocampus." (PMID 23776493, 2013). "Based on the author’s knowledge, muscular KIF5B expression in diabetes has not been investigated yet, but it has been reported that KIF5B in skeletal muscles is responsible for protein transportation." (PMID 33953268, 2021). "Thus, ER sheets may serve as the place of KIF5B- and Hsp90-dependent chaperone exchange, which predominantly facilitates CaV1.2 production in beta cells and properly enterprises GSIS against diabetes." (PMID 39322740, 2024).
diabetes (continued). "Therefore, we propose that the beneficial effects of ET on diabetes might be related to GAP-43 and KIF5B expression and their co-localization in skeletal muscle." (PMID 33953268, 2021). "Although, the effect of hyperglycemia on KIF5B expression in skeletal muscle fiber is not elucidated yet, KIF5B might be a possible marker of muscle impairment in diabetes." (PMID 33953268, 2021). "In this study, we found that there is an increase in KIF1A and KIF5B levels in the hippocampus at 8 weeks after the onset of diabetes, with no changes in dynein levels, suggesting that the anterograde transport may be impaired in the hippocampus." (PMID 23776493, 2013). "We show that short-term diabetes alters mRNA levels and axoplasm protein contents of kinesin family member KIF1A, KIF5B, KIF5A and Myosin Va in male but not in female rats." (PMID 29351809, 2018). "Diabetes increased the expression and immunoreactivity of KIF1A and KIF5B in the hippocampus, but no alterations in dynein were detected." (PMID 23776493, 2013).
Histiocytosis (5 papers, 2021 to 2025). An excessive number of histiocytes (tissue macrophages). "ALK-positive histiocytosis is characterized by the presence of ALK fusions (most frequently KIF5B::ALK) and a remarkable response to ALK inhibitor therapy." (PMID 40700600, 2025). "KIF5B has been shown to be the most common fusion-partner gene in ALK-positive histiocytosis, whereas CLTC, TPM3, EML4, and TFG have only been infrequently recorded." (PMID 40700600, 2025). "KIF5B-ALK has emerged as the most frequent molecular alteration in ALK-positive histiocytosis (83%, 44/53)." (PMID 36915094, 2023). "Here, we report a case of a 3-year-old boy with ALK-positive histiocytosis with systemic masses that was identified to harbor KIF5B-ALK gene fusion." (PMID 35982724, 2022). "ALK-positive histiocytosis is characterized by expression of ALK1 by immunohistochemical stain and shows fusion of the ALK gene with different partners, most commonly KIF5B." (PMID 33973641, 2021). "ALK-positive histiocytosis is a relatively new histiocytic proliferation disease with a characteristic gene translocation involving fusion of the ALK gene with different partners, mostly KIF5B." (PMID 33973641, 2021). "Therefore, ALK-positive histiocytosis was suspected and confirmatory molecular testing for the presence of ALK gene translocation, which was performed at an outside facility, showed the presence of KIF5B-ALK gene fusion by RT-PCR, confirming the diagnosis." (PMID 33973641, 2021).
melanoma (5 papers, 2015 to 2025). A malignant, usually aggressive tumor composed of atypical, neoplastic melanocytes. "Both control and Kif5b-deficient mice were implanted subcutaneously with a highly immunogenic OVA-expressing B16 melanoma cell line." (PMID 32286311, 2020). "Interestingly, the mRNA of motor protein KIF1C, a component of the Kinesin superfamily like Kif5b, interacts with its encoded protein, localizing asymmetrically in protruding end of melanoma cells." (PMID 41163196, 2025). "miR-203 promotes melanogenesis through the CREB1/MITF/Rab27a pathway by targeting Kif5b in melanoma." (PMID 34831071, 2021). "When we specifically knocked down Kif5b isoform in these cells with two independent siRNAs, perinuclear melanosome aggregation occurred, a finding that was consistent with a recent report on human melanoma cells." (PMID 25649263, 2015).
thyroid cancer (4 papers, 2012 to 2021). "While RET mutations have been associated with thyroid cancer for many years, the discovery of KIF5B-RET fusions in non-small cell lung cancer (NSCLC) has created particular excitement." (PMID 30038711, 2018). "Analysis of lung and thyroid cancer tissues showed a positive rate by RET fusion partners such as KIF5B and CCDC6, and their sensitivities were 100%." (PMID 34497761, 2021). "Ponatinib potently inhibits activating variants of RET in models of thyroid cancer, and others have shown that ponatinib inhibits KIF5B-RET fusions in genetically engineered models (but not patient-derived xenograft [PDX] models)." (PMID 30038711, 2018).
Glucose intolerance (3 papers, 2020 to 2025). Glucose intolerance (GI) can be defined as dysglycemia that comprises both prediabetes and diabetes. "The physiological significance of KIF5B was further confirmed when adipose-specific deletion of KIF5B, in mice, caused glucose intolerance and insulin resistance." (PMID 40806697, 2025).
HIV-1 infection (3 papers, 2016 to 2020). The type species of lentivirus and the etiologic agent of acquired immunodeficiency syndrome (AIDS). "Here, we show that the Kinesin-1 motor, KIF5B, induces a relocalization of the nuclear pore component Nup358 into the cytoplasm during HIV-1 infection." (PMID 27327622, 2016). "In this study, we demonstrate that HIV-1 infection induces the KIF5B dependent relocalization of Nup358." (PMID 27327622, 2016). "Interestingly, Nup358 was also reported to be translocated into the cytoplasm in a CA-and kinesin family member 5B (KIF5B)-dependent manner during HIV-1 infection and this cytoplasmic translocation is suggested to be important for HIV-1 nuclear entry." (PMID 31028522, 2019). "KIF5B knockdown inhibited the NUP358 relocalization induced by HIV-1 infection." (PMID 27327622, 2016).
Insulin resistance (3 papers, 2020 to 2025). Increased resistance towards insulin, that is, diminished effectiveness of insulin in reducing blood glucose levels. "CMKLR1 is linked to nuclear factor kappa-light-chain-enhancer of activated B cells (NF-κB) activation and insulin signaling, and kinesin family member 5B (KIF5B) is associated with insulin resistance and obesity." (PMID 37958793, 2023). "Another study demonstrated that the deletion of Kif5b‐induced obesity and insulin resistance." (PMID 33200553, 2020).
metastatic cancer (3 papers, 2021 to 2022). A carcinoma which has spread from the original site of growth to another anatomic site. "NOTCH2, NOTCH2NL, KIF5B, and ERBB4 are highly expressed in primary cancer, while ERBB2, CLDN11 and CDK12 are overexpressed in metastatic cancer." (PMID 33441952, 2021). "Population-wide comparison between TT and LN single cells revealed that NOTCH2, NOTCH2NL, KIF5B, and ERBB4 are highly expressed in primary cancer, while CDK12, ERBB2, and CLDN11 are overexpressed in metastatic cancer." (PMID 33441952, 2021).
Obesity (3 papers, 2017 to 2023). Accumulation of substantial excess body fat. "In this study, selective deletion of conventional kinesin heavy chain (Kif5b) in adipose tissue, which mediates adiponectin secretion, exacerbates high-fat diet (HFD)-induced obesity and its associated metabolic disorders." (PMID 28758929, 2017).
pancreatic cancer (3 papers, 2020 to 2024). "Recently, KIF5B has been identified as a promising early biomarker in the advanced stage of pancreatic cancer." (PMID 39507532, 2024). "A network prediction mapping analysis was performed to investigate pancreatic cancer-related pathways that are activated on the activation of both KIF5B and SFRP2." (PMID 36002889, 2022). "Thus, there is a distinct possibility that Kif5b could potentially be a viable and novel marker worthy of being further investigated in pancreatic cancer." (PMID 36002889, 2022). "A network mapping of direct and indirect relationships between KIF5B and SFRP2 was done by overlaying their connective map with pathways that are regulated by pancreatic cancer." (PMID 36002889, 2022). "Proteomic characterization of EVs mimicking “first contact” conditions of tumor-stromal interactions resulted in the identification of KIF5B and SFRP2 as promising early biomarkers that are expressed in progressive stages of pancreatic cancer." (PMID 36002889, 2022). "Among all the proteins that were analyzed (MMP3, KIF5B, SFRP2, and LOXL2), KIF5B and SFRP2 show promise as bona fide early pancreatic cancer biomarkers expressed in progressive stages of pancreatic cancer." (PMID 36002889, 2022). "KIF5B and SFRP2 show promise for early detection and investigation in progressive pancreatic cancer." (PMID 36002889, 2022). "All these findings suggest that KIF5B and SFRP2 are promising early pancreatic cancer markers." (PMID 36002889, 2022). "Additionally, a human TMA was used to analyze the expression of KIF5B and SFRP2 in progressive stages of pancreatic cancer." (PMID 36002889, 2022).
prostate carcinoma (3 papers, 2016 to 2024). A carcinoma that arises from epithelial cells of the prostate gland. "KIF5B is increased in prostate cancer cells, but whether it mediates the ability of prostate cancer CTCs to downregulate MHC class I as a mechanism for immune evasion has not been explored." (PMID 39796673, 2024). "In this report we demonstrated that Arl8b, through its interaction with kinesin Kif5b, is required for this response in multiple cell lines and that by depleting Arl8b, protease secretion is reduced and prostate cancer invasive growth within a 3D ECM model is greatly impaired." (PMID 27105540, 2016). "We did not observe changes to prostate cell phenotype or migration from KIF5B knockdown, yet KIF5C silencing significantly increased migration of prostate cancer cells." (PMID 39217195, 2024).